PIN1 (peptidylprolyl cis/trans isomerase, NIMA-interacting 1)
Diseases named in the same sentence as PIN1 in open-access papers (continued):
Sharing a sentence is not in itself a finding about the gene and the disease.
neurological diseases (10 papers, 2017 to 2024). "Both of these processes have been implicated in neurological disorders and, moreover, two PIN1 single nucleotide polymorphisms (SNPs) are considered risk factors for sporadic AD." (PMID 37759260, 2023). "These examples highlight the involvement of Pin1 in various neurological disorders, especially as Pin1 regulates various pro-apoptotic proteins that are involved in neuronal death." (PMID 38727267, 2024). "Our novel data builds upon the FK506 literature in neurological disorders by showing reduction in neurodegeneration and neuroinflammation through the normalization of CN and Pin1 activity." (PMID 37849016, 2023). "The peptidyl-prolyl isomerase Pin1 has wide-ranging influences on the occurrence and development of neurological diseases." (PMID 36304997, 2022). "The loss of Pin1 activity could affect conformational and functional changes in PSD proteins in AD and in other neurological diseases." (PMID 28458925, 2017).
metabolic disorders (7 papers, 2016 to 2024). "Taking these results together, changes in Pin1 that depend on nutritional status appear to be tightly linked to metabolic disorders and Pin1 may thus be a useful biomarker." (PMID 27618008, 2016). "In our study, we identified that Pin1 has a positive function in metabolic disorders in hepatocytes and the liver." (PMID 38892011, 2024). "In the case of metabolic disorders, Pin1 regulates insulin secretion via regulating pancreatic beta-cell proliferation." (PMID 36111342, 2022). "Overall, Pin1 plays a catalytic role in metabolic disease in the pathogenesis of NAFLD." (PMID 38892011, 2024). "Nevertheless, we think that PIN1 could play a role in regulating the metabolic phenotype of skeletal muscles and might represent a future target to counteract muscle and metabolic diseases." (PMID 38786739, 2024). "This study further highlights the role of Pin1 in metabolic diseases." (PMID 36111342, 2022). "However, Pin1 interacts with or regulates other key molecules involved in metabolic diseases, including obesity-related factors AMPK 62-65, PPARγ 66, and PRDM16 67; osteoporosis-related factors Runx2 68-70 and BMP2 71; and Nash-related factors Smad2/Smad3 and the TGF-β1 pathway." (PMID 33537091, 2021).
cardiovascular diseases (3 papers, 2021 to 2022). "Taken together, Pin1 potentially plays a double-edged role in regulating the pathogenesis of cardiovascular diseases under different circumstances." (PMID 33537091, 2021). "Further detailed investigations are needed to reveal the function of Pin1 in cardiovascular disease." (PMID 33537091, 2021). "Focusing on the vascular homeostasis, Pin1 may drive different outcomes, from vascular cell proliferation, to apoptosis, immune response and inflammation, with implication in many cardiovascular diseases." (PMID 34943794, 2021).
immune disorders (3 papers, 2015 to 2024). "Finally, we will address several physiological cytokines and immune disorders associated with the function of Pin1." (PMID 25874604, 2015).
skeletal diseases (2 papers, 2013 to 2016). "In this study, we demonstrate for the first time that PIN1 also control bone homeostasis suggesting it may contribute to the pathogenesis of skeletal diseases." (PMID 23675491, 2013).
bacterial infection (1 paper, 2012). "The absence of Pin1 impairs FL-induced expansion of CD8+ cDC and also prevents robust proliferation of WT CD8+ T cells following bacterial infection in mice." (PMID 22238658, 2012).
brain diseases (1 paper, 2018). "We speculate that Pin1 might control many brain diseases by regulating CaMKII activity properly." (PMID 30532705, 2018).
inflammation (1 paper, 2018). Aberrant reaction of the microcirculation characterized by movement of fluid and leukocytes from the blood into extravascular tissues. "Here the authors show, using biochemical, structural and patient data, that upon IL-33 or allergic challenge, the isomerase Pin1 modifies IRAK-M to control the production of pro-inflammatory cytokines in the setting of airway inflammation." (PMID 29686383, 2018). "Upon IL-33-induced airway inflammation, PIN1 is activated for binding with and isomerization of IRAK-M, resulting in IRAK-M nuclear translocation and induction of selected proinflammatory genes in dendritic cells." (PMID 29686383, 2018).
kidney diseases (1 paper, 2024). "In contrast, Pin1 has been linked to the occurrence and progression of various kidney diseases." (PMID 38711994, 2024). "In the future, regulating the expression of Pin1 is expected to be beneficial in the treatment of kidney diseases." (PMID 38711994, 2024). "Recently, multiple studies have highlighted the significant roles of Pin1 and its inhibitors in the pathophysiology of kidney diseases." (PMID 38711994, 2024). "Given the varying effects of Pin1 on oxidative stress-related processes, its role in kidney disease is a compelling and significant area of research." (PMID 38711994, 2024). "The representative therapeutic agent Juglone has emerged as a potential treatment for inhibiting Pin1 activity and mitigating kidney disease." (PMID 38711994, 2024). "Understanding the role of Pin1 in kidney diseases is expected to provide new insights into innovative therapeutic interventions and strategies." (PMID 38711994, 2024). "The role of Pin1 in mouse kidney development and kidney disease is of significant interest." (PMID 38711994, 2024). "Furthermore, it is crucial to emphasize the need for both clinical and preclinical trials to elucidate the effects of Pin1 on kidney disease." (PMID 38711994, 2024). "Consequently, this review delves into the molecular mechanisms of Pin1 and its relevance in kidney disease, paving the way for novel therapeutic approaches." (PMID 38711994, 2024). "Hence, we present a concise overview of Pin1, focusing on its structural biology and discussing the existing knowledge regarding its involvement in various kidney diseases." (PMID 38711994, 2024). "For example, gene therapy may be used to modify Pin1 expression for treating kidney disease or inhibitors of Pin1 may be used to treat AKI and CKD." (PMID 38711994, 2024). "Alterations in Pin1 expression levels play pivotal roles in both physiological processes and multiple pathological conditions, especially in the onset and progression of kidney diseases." (PMID 38711994, 2024). "In conclusion, Pin1 plays a vital role in the pathogenesis of kidney diseases, and modulating its expression (either upregulation or downregulation) may offer effective therapeutic strategies for various kidney disorders." (PMID 38711994, 2024). "However, the regulatory role of Pin1 in other kidney diseases remains unclear." (PMID 38711994, 2024).
PIN1 also shares sentences with these, for which no sentence is quoted: laryngeal squamous cell carcinoma (4 papers); non-alcoholic steatohepatitis (4); Allergy (2); amyloid (2); brain ischemia (2); cutaneous melanoma (2); endometrial carcinoma (2); follicular adenoma (2); gallbladder cancer (2); ischemia (2); lupus (2); preeclampsia (2); schizophrenia (2); squamous cell carcinoma of the head and neck (2); testis cancer (2); adenocarcinoma (1); age (1); anaplastic astrocytoma (1); Arrhythmia (1); astrocytoma (1); autoimmune disease (1); Autoimmunity (1); behavior disorder (1); breast (1); Burkitt lymphoma (1); Cerebral ischemia (1); cholangiocarcinoma (1); episodic ataxia type 2 (1); essential hypertension (1); experimental autoimmune encephalomyelitis (1).
A further 27 diseases each share a sentence with PIN1 in 1 paper.